GRB7 (growth factor receptor bound protein 7)
Diseases named in the same sentence as GRB7 in open-access papers (continued):
Sharing a sentence is not in itself a finding about the gene and the disease.
ovarian carcinoma (continued). "GRB7 targeting inhibits ovarian cancer tumor growth through the ERK inhibition." (PMID 34718347, 2022). "Therefore, the suppressive effect of GRB7 on VEGFA is consistent with GRB7 playing a role in regulating angiogenesis in ovarian cancer." (PMID 34783299, 2021). "In view of the important role of angiogenesis in ovarian cancer growth and metastasis, we hypothesized that GRB7 might promote the growth and metastasis of ovarian cancer cells by regulating angiogenesis to increase their blood supply." (PMID 34783299, 2021). "In conclusion, GRB7 plays a role in regulating angiogenesis in ovarian cancer; reducing its expression may be a promising strategy to suppress angiogenesis in patients with ovarian cancer." (PMID 34783299, 2021). "In the current study, we aimed to determine whether GRB7 plays a role in regulating angiogenesis in ovarian cancer." (PMID 34783299, 2021). "Membrane expression of GRB7 protein has been observed in ovarian cancer samples." (PMID 32595827, 2020). "It has been previously shown that GRB7 expression is associated with high-grade ovarian cancer, but the correlation between GRB7 overexpression and clinical outcome is not known." (PMID 32595827, 2020). "As with IDC of the breast, membrane expression of GRB7 is primarily seen in ovarian cancer samples with high GRB7 cytoplasmic expression (3+) but only a fraction of ovarian cancer samples with high cytoplasmic expression of GRB7 protein (3+) has membrane accentuation." (PMID 32595827, 2020). "Interestingly, the concomitant increase of GRB7, ERK phosphorylation and FOXM1 is associated with high-grade ovarian cancers." (PMID 23285101, 2012). "Importantly, we show that these factors are coordinately regulated in GRB7/ERK/FOXM1 signaling axis in ovarian cancer cells." (PMID 23285101, 2012). "But inhibition of ERK signaling by U0126 or PD98059 could reduce the level of FOXM1 in GRB7-overexpressing ovarian cancer cells, suggesting that GRB7, ERK and FOXM1 are regulated orderly." (PMID 23285101, 2012). "Collectively, our findings confer that targeting GRB7/ERK/FOXM1 signaling cascade may be a promising molecular therapeutic choice in combating ovarian cancer." (PMID 23285101, 2012). "Indeed, the data indicate that GRB7 could impact ovarian cancer development via a variety of signaling channels." (PMID 39204147, 2024). "We hypothesized that GRB7 may play an important role in angiogenesis in ovarian cancer." (PMID 34783299, 2021). "Additionally, we performed GRB7 IHC on both breast and ovarian cancer TMAs." (PMID 32595827, 2020). "In this study, we found that GRB7 (P<0.0001), ERK phosphorylation (P<0.0001) and FOXM1 (P = 0.001) were frequently increased and associated with high-grade tumors, as well as a high tendency in association with advanced stage ovarian cancer by immunohistochemical analysis." (PMID 23285101, 2012). "The results showed that GRB7 was positively correlated with HER2 and CDH1 in CCLE proteomics data, and GRB7 was positively correlated with HER2 and HER2_pY1248 in pan-cancer and ovarian cancer." (PMID 39204147, 2024). "MiR-193a-3p has been reported to target the GRB7 and MAPK/ERK pathways in ovarian cancer, hence promoting the aggressiveness of the malignancy." (PMID 39204147, 2024). "The protein expression of GRB7 and CD31 in ovarian cancer tissues was analyzed using immunohistochemistry." (PMID 34783299, 2021). "Immunohistochemistry on tissue microarray showed that GRB7 and platelet endothelial cell adhesion molecule-1 (PECAM-1/CD31) protein expression were positively correlated in ovarian cancer tissues." (PMID 34783299, 2021). "Therefore, we hypothesized that GRB7 may play a role in regulating angiogenesis in ovarian cancer." (PMID 34783299, 2021). "We found that GRB7 and CD31 expression levels in ovarian cancer tissues were significantly correlated." (PMID 34783299, 2021).
ovarian carcinoma (continued). "Because of the dissimilar location of GRB7 and CD31 expression in ovarian cancer tissues, a contactless transwell co-culture system was designed to investigate the role of GRB7 in angiogenesis." (PMID 34783299, 2021). "Despite this observation, we found that the regions highly expressing GRB7 and CD31 in ovarian cancer tissues were different." (PMID 34783299, 2021). "All in all, these findings indicate that GRB7, ERK phosphorylation and FOXM1 form an oncogenic convergence in high-grade ovarian cancer pathogenesis." (PMID 23285101, 2012). "Clinico-pathological analysis of GRB7, ERK phosphorylation and FOXM1 expressions in ovarian cancer tissue array (OVC1021)." (PMID 23285101, 2012). "Intriguingly, the expressions of GRB7 (P<0.0001), ERK phosphorylation (P<0.001) and FOXM1 (P<0.001) showed a significant stepwise increase pattern along Grade 1 to Grade 3 ovarian cancers." (PMID 23285101, 2012). "Our results emphasize the importance of the GRB7/ERK/FOXM1 pathway in tumorigenic properties and argue this pathway for a promising therapeutic target in high-grade ovarian cancer." (PMID 23285101, 2012). "We have previously reported that GRB7, ERK phosphorylation and FOXM1 are overexpressed in ovarian cancer samples particularly in high-grade tumors." (PMID 23285101, 2012). "In this study, we show that the expressions of GRB7, ERK and FOXM1 were significantly correlated with the progression of ovarian cancer." (PMID 23285101, 2012). "Taken together, these data indicate there is a close interplay among GRB7, ERK activity and FOXM1 in regulating ovarian cancer oncogenesis particularly in high-grade tumor." (PMID 23285101, 2012). "In this study, we present evidence that GRB7, ERK phosphorylation and FOXM1 are increased in ovarian cancer." (PMID 23285101, 2012). "The analysis of these datasets revealed a predominant expression of GRB7 in malignant cells as opposed to immune cells, a pattern consistent across not only ovarian cancers but also a broad spectrum of other cancer types." (PMID 39204147, 2024). "To test this hypothesis, we first analyzed the expression of GRB7 and CD31 proteins in ovarian cancer tissues by immunohistochemistry." (PMID 34783299, 2021). "In ovarian cancer, MIR193A is silenced by methylated modification and down regulation of MIR193A expression promotes tumor aggressiveness by losing function of targeting GRB7 and MAPK/ERK pathways." (PMID 31523496, 2019). "The prognostic significance of GRB7 expression has otherwise not been reported in ovarian cancer." (PMID 32595827, 2020). "On the other hand, Grb7, but not Grb7v, facilitates the migration and invasion of ovarian cancer." (PMID 31083325, 2019). "Recently, a study indicated a negative correlation between miR-193a-3p and GRB7 in ovarian cancers." (PMID 31083325, 2019). "Here, our data show that GRB7 regulates ERK activity and the FOXM1 expression orderly and is in agreement with our previous reports, indicating that the overexpressed GRB7 enhances ovarian cancer cell growth and cell migration/invasion through elevating ERK and FOXM1 activities." (PMID 23285101, 2012). "Given that the increased GRB7, ERK phosphorylation and FOXM1 significantly correlate with high-grade ovarian tumor, they may be regulated coordinately in order to mediate oncogenic functions in ovarian cancer progression." (PMID 23285101, 2012). "We also describe the regulatory mechanism of GRB7/ERK/FOXM1 signaling cascade and the inhibition of this signaling using either the chemical inhibitor U0126 or FOXM1 inhibitor Thiostrepton could remarkably abrogate the ovarian cancer cell migration/invasion, and in vitro and in vivo tumor growth." (PMID 23285101, 2012). "In the present study, we did not explore the mechanism by which GRB7 regulates the expression and secretion of VEGFA in ovarian cancer cells." (PMID 34783299, 2021).
esophageal cancer (8 papers, 2008 to 2024). A primary or metastatic malignant neoplasm involving the esophagus. "It has been reported that GRB7 is a driver gene associated with poor prognosis in esophageal cancer and which has an effect on the proliferation, migration and invasion capacities of cells." (PMID 28169357, 2017). "Overall, the lack of preclinical evidence with regard to the functional role of GRB7 amplification and/or overexpression in oesophageal cancer is preventing the identification of any potential therapeutic benefits of targeting GRB7 in this disease." (PMID 32737994, 2020). "In human esophageal carcinoma, the tyrosine phosphorylation of Grb7 has been detected in response to EGF or fibronectin stimulation." (PMID 31083325, 2019). "Moreover, the overexpression of Grb7 is positively correlated with the presence of lymph node metastases of esophageal carcinomas, suggesting a critical role of Grb7 in metastatic progression." (PMID 31083325, 2019). "The coexpression of Grb7 with the ERBB family, especially EGFR and ERBB2, is significantly correlated with the invasion of advanced esophageal carcinomas." (PMID 31083325, 2019). "Genes co-amplified with ERBB2 (GRB7, MIEN1, PGAP3, and STARD3) exhibited the highest amplification frequency in esophageal cancer, followed by stomach, breast, uterine, and bladder cancer." (PMID 29190909, 2017). "The GRB7 and ERBB2 genes are co-amplified and/or overexpressed in human gastric and esophageal carcinoma cell lines, and in primary gastric and esophageal cancers, particularly within the lower segment of the esophagus." (PMID 19424485, 2008). "Actually, the coexpression of Grb7 with EGFR was significantly related to advanced esophageal carcinomas with extramucosal invasion, whereas this phenomenon was not induced by the sole expression of Grb7 or EGFR." (PMID 31083325, 2019).
pancreatic cancer (8 papers, 2002 to 2024). "GRB7 (growth factor receptor-bound protein 7) was found to be overexpressed in pancreatic tumor than normal pancreatic tissue and was associated with regional lymph node metastatic spread of pancreatic cancer." (PMID 26294325, 2015). "Growth factor receptor bound protein 7 (Grb7) is an adaptor protein with established roles in the progression of both breast and pancreatic cancers." (PMID 29018805, 2017). "In a separate study, the same Grb7 inhibitor was demonstrated to significantly attenuate the migratory potential of pancreatic cancer cells." (PMID 17894853, 2007). "Interestingly, analysis of a series of cancer types that harbored aberrant RAS and/or RAF mutations as oncogenic drivers indicated that the expression of GRB7 in lung carcinoma and pancreatic cancer was much higher than that in melanoma." (PMID 34718347, 2022). "Apoptosis analysis in A549 (lung cancer) and CFPAC-1 (pancreatic cancer) cells was performed to determine whether GRB7 mediates MEKi resistance in other RAS-driven cancer types." (PMID 34718347, 2022). "Notably, we observed similar results in KRAS mutant lung and pancreatic cancer cells, implying that GRB7 plays a critical role in RAS-driven cancer cells in the presence of MEKi." (PMID 34718347, 2022). "In a mouse model, Grb7 peptide inhibitor, which selectively blocks the interactions between Grb7 and ERBB family proteins or FAK as well as blocking the phosphorylation of Grb7 protein, significantly ablates the peritoneal metastasis of pancreatic cancer cells." (PMID 31083325, 2019). "Thus, caveolin-1 might cooperate with other molecules, such as c-Src and Grb7, to stimulate tumour growth in pancreatic carcinoma." (PMID 12402154, 2002). "Of note, G7-18NATE also selectively blocked the interaction between Grb7 and FAK and blocked the tyrosine phosphorylation of Grb7, as well as significantly reducing the migration and peritoneal metastasis of pancreatic cancer in preclinical studies." (PMID 31083325, 2019). "Furthermore, in a recent study by Tanaka and colleagues, G7-18NATE was shown to not only selectively block the interaction between Grb7 and FAK in vivo, but to significantly attenuate the migration of pancreatic cancer cells." (PMID 17894853, 2007).
bladder cancer (7 papers, 2017 to 2024). "In general, this study shows that GRB7 is upregulated in human bladder cancer and plays an important role in promoting proliferation and tumorigenesis via phosphorylated-AKT pathway, which suggests a potential role of GRB7 as a diagnostic marker and valuable therapeutic target in bladder cancer." (PMID 33162827, 2020). "Silencing GRB7 in cell experiments and mouse tumor models has led to reduced proliferation and tumorigenesis in bladder cancer." (PMID 39360313, 2024). "Previous study has shown that high GRB7 expression significantly promoted proliferation and tumorigenesis of bladder cancer." (PMID 38129809, 2023). "The Cancer Genome Atlas (TCGA) database was selected to analyze mRNA levels of GRB7 in bladder cancer." (PMID 33162827, 2020). "Meanwhile, RT-qPCR analysis and Western blot analysis revealed that the mRNA level and protein level of GRB7 were both upregulated in malignant bladder cancer tissues compared to that in adjacent normal tissues." (PMID 33162827, 2020). "The mean value of GRB7 mRNA was used as the dividing line, and 408 cases of bladder cancer were divided into GRB7 high expression group (GRB7-H) and GRB7 low expression group (GRB7-L)." (PMID 33162827, 2020). "This study found that the expression of GRB7 is elevated in human bladder cancer, and the abnormal expression of GRB7 promotes the proliferation and tumorigenesis of bladder cancer cells by promoting cell cycle G1/S transition." (PMID 33162827, 2020). "Taken together, phospho-AKT pathway mediates GRB7-induced cell proliferation and tumorigenesis in bladder cancer cells." (PMID 33162827, 2020). "Taken together, the results indicate that GRB7 plays a positive role in the tumorigenesis of bladder cancer cells." (PMID 33162827, 2020). "In the present study, we find that GRB7 mRNA and protein expression are upregulated in bladder cancer." (PMID 33162827, 2020). "Given the importance of AKT in bladder cancer, we sought to investigate the role of GRB7 in AKT signaling." (PMID 33162827, 2020). "Our results indicate that GRB7 plays an important role in promoting proliferation and tumorigenesis of bladder cancer." (PMID 33162827, 2020). "The GRB7 mRNA was upregulated in bladder cancer samples (Tumor) compared to that in normal tissue samples (19 cases, Normal) (P < 0.001)." (PMID 33162827, 2020). "In addition, GRB7 mRNA was upregulated in bladder cancer samples and Overexpression of GRB7 significantly promoted bladder cancer proliferation and tumorigenesis." (PMID 36642706, 2023). "The study is aiming at investigating the expression and function of GRB7 in bladder cancer." (PMID 33162827, 2020). "Taken together, GRB7 is upregulated in human bladder cancer indicated by these results." (PMID 33162827, 2020). "Overexpressing GRB7 significantly promoted the proliferation and tumorigenesis of bladder cancer." (PMID 33162827, 2020). "These in vitro results indicate that GRB7 may play a role in promoting the proliferation of bladder cancer cells." (PMID 33162827, 2020). "The mRNA expression of GRB7 in 427 bladder cancer tissues in the TCGA database was analyzed." (PMID 33162827, 2020). "GRB7 mRNA was upregulated in bladder cancer samples compared with that in normal tissue samples." (PMID 33162827, 2020). "In addition, why GRB7 is elevated in bladder cancer is also a problem worth studying." (PMID 33162827, 2020). "However, the role of GRB7 in the malignant processes of bladder cancer is unknown." (PMID 33162827, 2020). "RT-qPCR and Western blot were conducted to detect the expression of GRB7 in normal bladder epithelial cells, seven bladder cancer cell lines and eight pairs of malignant/nonmalignant bladder tissues." (PMID 33162827, 2020). "Growth factor receptor-bound protein 7 (GRB7) has been found closely related to the occurrence and development of various tumors, but its function in bladder cancer has not yet been elucidated." (PMID 33162827, 2020).
cervical cancer (6 papers, 2020 to 2024). A primary or metastatic malignant neoplasm involving the cervix. "Overexpression of GRB7 in cervical cancer has been found to promote cervical cancer cell invasion and inhibit cell apoptosis, while knockdown of GRB7 in esophageal adenocarcinoma reduces proliferation and induces apoptosis." (PMID 36686796, 2022). "In cervical cancer, high expression of GRB7 promotes distant invasion of cervical cancer and inhibits apoptosis." (PMID 33162827, 2020). "A study on cervical cancer found that GRB7 protein expression was significantly higher in cancer tissues than in non-cancer tissues, and was associated with age, tumor size, serosal invasion, degree of differentiation, tumor stage, early or advanced stage, and lymph node metastasis." (PMID 36642706, 2023). "In addition, GRB7 showed clinic-pathological significance in cervical cancer, while high GRB7 levels were correlated with age, tumor size and stage, serosal invasion, lymph node metastasis, lower overall survival rate." (PMID 32595827, 2020).
triple-negative breast carcinoma (6 papers, 2013 to 2025). An invasive breast carcinoma which is negative for expression of estrogen receptor (ER), progesterone receptor (PR), and human epidermal growth factor receptor 2 (HER2). "It has been shown that in CM cells, clofarabine (Clo) induces GSDME-mediated apoptosis by activating T cell immunity through CCL5 and CXCL10, and FAK-mediated phosphorylation of GRB7 plays a key role in triple-negative breast cancer (TNBC) cell migration." (PMID 41216288, 2025). "A low (1+) to moderate (2+) level of GRB7 protein expression is noted in triple negative breast cancers." (PMID 32595827, 2020). "In pancreatic, oesophageal and triple negative breast cancers, Grb7 drives migratory and invasive events, with Grb7 knockdown inhibiting these processes when tested in vitro." (PMID 29018805, 2017). "In addition, GRB7 expression is found to be an adverse prognostic factor for triple negative breast cancer (TNBC), both in vivo and in vitro." (PMID 32595827, 2020). "Cytoplasmic GRB7 expression was seen predominantly in HER-2 positive and, to a lesser extent, triple negative breast cancer." (PMID 32595827, 2020). "Two cell lines were selected, the HER2+ve cell line SKBR-3 that massively overexpresses Grb7 along with HER2, and MDA-MB-231 that is a triple negative breast cancer cell (TNBC) line that expresses only low levels of Grb7." (PMID 31627265, 2019). "Grb7 is a key signaling molecule in the progression of HER2 positive and triple negative breast cancers." (PMID 27257138, 2016). "When we analyzed the sections with triple negative breast cancer (TNBC, n = 48), we found 4 with medium (2+) GRB7 expression, 10 with weak (1+) GRB7 expression, and 34 samples with no GRB7 expression." (PMID 32595827, 2020).
breast tumors (5 papers, 2013 to 2023). "HER-2 and GRB7 protein expression from 613 frozen breast tumors was determined by Western analysis." (PMID 24102037, 2013).
colon cancer (5 papers, 2022 to 2024). "Due to its overexpression and possible role in the initiation and spread of several malignancies, including breast and colon cancer, GRB7 has become a noteworthy molecule." (PMID 39204147, 2024).
hepatocellular carcinoma (4 papers, 2024 to 2025). A malignant tumor that arises from hepatocytes. "GRB7 has been linked with several tissues in the context of cancer progression, including liver (hepatocellular carcinoma) and pancreas, and a contribution to Insr signalling functions in these tissues cannot be excluded." (PMID 39343875, 2024).
invasive breast carcinoma (3 papers, 2010 to 2018). A carcinoma that infiltrates the breast parenchyma. "Nearly 18% of clinical breast invasive carcinoma samples in TCGA database had shown high amplification of the genomic region that harbored ERBB2, GRB7 and other neighboring genes." (PMID 29414922, 2018). "Interestingly, GRB7 and ERBB2 are co-amplified in 15% of invasive breast cancers and 17–19% of gastric adenocarcinomas." (PMID 24874471, 2014).